Y_RNA (Y RNA )
Gene: Miscellaneous RNA gene on chromosome 18 (9,249,649 to 9,249,746, reverse strand). Ensembl gene ENSG00000200883.
Homologues: Orthologues: chimpanzee Y_RNA (100% identical), macaque Y_RNA (93% identical). Paralogues in human: RNY3 (86% identical), Y_RNA (85% identical), Y_RNA (84% identical), RNY3P1 (83% identical), RNY3P11 (83% identical), Y_RNA (83% identical), Y_RNA (82% identical), Y_RNA (81% identical), RNY3P9 (80% identical), Y_RNA (80% identical), RNY3P14 (79% identical), RNY3P2 (79% identical), and 88 more.